MMP2 (matrix metallopeptidase 2)
Diseases named in the same sentence as MMP2 in open-access papers (continued):
Sharing a sentence is not in itself a finding about the gene and the disease.
tumor (continued). "Furthermore, MMP-2 and -9, which play a crucial role in basement membrane degradation and tumor cell invasion, also decreased following the combined vorinostat and EGCG treatment and the expression level of MMP-2 or -9 was significantly lower at drug combination than single treatment." (PMID 23864881, 2013). "The role of virus proteins on tumor invasiveness was first noted in a study demonstrating in hepatoma cell line the ability of hepatitis B virus (HBV) X protein to induce expression of matrix metalloproteinases MMP-2 and MT1-MMP (MMP-14), via a Cox 2-dependent mechanism." (PMID 23967226, 2013). "Thus, TAGLN may enhance tumor metastasis through the MMP-2 enzymes degrade the basement membranes (eg. collagen IV)." (PMID 23510049, 2013). "The tumor-promoting role of IL-6 may be exerted via MMP-2, whose production is increased by IL-6." (PMID 24023566, 2013). "MMP-2 not only regulates the adhesion between cells thereby affecting invasive metastasis of tumor cell, but also induce activation of extracellular protein, and plays a key role in attracting inflammatory cells and spontaneously stimulating migration of tumor cells." (PMID 24245968, 2013). "Our results indicated that expression levels of miR-29b, miR-125a-5p, miR-205, and miR-221 may be useful as diagnostic markers of sensitivity to Gem treatment, and that PIK3R1 and MMP-2 could become molecular targets of anti-tumor therapies for patients with CCA." (PMID 24147037, 2013). "Therefore, MMP-2 could potentially contribute to tumor progression via other mechanisms by processing molecules such as insulin like growth factor binding proteins (IGF-BPs), ephrin receptors and growth factors that contribute to angiogenesis." (PMID 22238668, 2012). "We also demonstrate that the anti-tumor activity of HSA/TIMP-2 is strongly associated with anti-angiogenesis attributed to a reduction of MMP-2 production but without inhibition of MT1-MMP, indicating that HSA/TIMP-2 plays a more complex role in anti-angiogenesis." (PMID 22545131, 2012). "In particular, MMP-2 acts mainly as virulence gene that may allow tumours to aggressively invade, colonize and grow in the lungs without markedly contributing to primary tumour growth, whereas MMP-1, determine metastatic potential of breast cancer to produce lung metastases." (PMID 23905066, 2012). "Therefore, we hypothesized that the decreased tumor survival in the MMP-2 null tumor-bone microenvironment may be osteoblast mediated, especially given their consistent positivity for MMP-2 expression in the tumor-bone microenvironment." (PMID 22238668, 2012). "High MMP-2 or MMP-9 expression in tumour or stromal cells might serve as prognostic predictors." (PMID 23107277, 2012). "To determine whether the effect of OSM on MMP2 expression was biologically relevant with respect to tumor cell invasion, we cultured canine (OSA8) or human (SJSA) OSA cells in inserts containing serum-free media and rhOSM (50 ng/mL) overlying a Matrigel substrate." (PMID 21481226, 2011). "Therefore, we performed immunohistochemistry for MMP-2 using the primary tumor sections." (PMID 20170548, 2010). "Likewise, MMP-2 levels were slightly lower in Dz13-treated tumours." (PMID 20334687, 2010). "However, in sections of ectopic tumours treated with Dz13, both MMP-2 and MMP-9 were downregulated." (PMID 20334687, 2010). "In addition, MMP-2 staining was specific for nuclei and cytoplasm of tumor cells." (PMID 19531263, 2009). "In addition, the decrease in ERK1 and ERK2 expression could be directly linked to decreased MMP2 expression and proteolytic activity in the GLA treated tumours." (PMID 19292920, 2009). "RECK may inhibit tumor invasion and metastasis by inhibiting the expression and activity of MMP-2." (PMID 19995435, 2009). "Increased expression and activity of MMP-2 could promote tumor invasion ability." (PMID 19995435, 2009).
tumor (continued). "Thus, altered splicing of the K-ras proto-oncogene could drive tumour progression in sporadic CRC by promoting MMP-2 expression, and inappropriate stem cell survival and self-renewal." (PMID 18554389, 2008). "As MMP‐2 is an important metalloproteinase for the invasion and dissemination of tumor cells, its functional relationship to the αvβ3 integrin expression might play a key role in tumor progression." (PMID 18394009, 2008). "Furthermore, we can provide a mechanistic link between β1- or β3-integrins and MMP-2 and may have implications for models of tumour cell invasion." (PMID 14647148, 2003). "In the tumor microenvironment, the AS16 peptide on the EV surface dissociates under MMP‐2 cleavage, facilitating EV internalization by tumor cells." (PMID 41178526, 2026). "Among these, MMP-2 and MMP-9 are the most extensively studied MMPs, as they facilitate tumor invasion and metastasis by degrading the ECM and basement membrane, thereby creating physical pathways for tumor dissemination." (PMID 41362727, 2026). "Gelatinases, or matrix metalloproteinases (MMP2) and (MMP9) play a pivotal role in tumour matrix degradation, thereby facilitating invasion, angiogenesis and metastasis." (PMID 42121921, 2026). "Elevated concentrations of MMP-2 and MMP-9, especially in urine, correlate with the clinical stage and histopathological malignancy of the tumor." (PMID 41977399, 2026). "For example, a peptide sequence recognized by matrix metalloproteinases 2 and 9 (MMP-2/9), such as PLGLAG, can be cleaved by extracellular MMPs in invasive tumors, thereby activating the conjugate within the tumor microenvironment." (PMID 41590805, 2026). "Upon fusion with tumor cell membranes, AUR is delivered intracellularly while the ACP complex remains anchored externally until triggered by ATP and MMP-2, releasing eCpG and activating dendritic cells." (PMID 41560835, 2026). "Immunohistochemical analysis showed that tumor tissues treated with high doses of VER exhibited reduced levels of PCNA, Bcl-2, vimentin, MMP-2, p-AKT, and p-PI3K compared with the control group." (PMID 41158757, 2026). "Mouse experiments demonstrated that octacosanol significantly reduced tumor p-AKT, MMP2, and MMP9 levels, indicating its in vivo anti-metastatic effect." (PMID 42193927, 2026). "MMP‐2 and MMP‐9 are gelatinases involved in collagen degradation, tumour invasion and angiogenesis, while MMP‐14 activates other MMPs and promotes tumour cell migration." (PMID 41546170, 2026). "Therefore, further in vivo investigations are important to determine whether these compounds can reach sufficient concentrations at tumor sites to exert meaningful biological effects, particularly in modulating MMP-2 and MMP-9 expression and thereby inhibiting tumor progression and metastasis." (PMID 40563423, 2025). "Reactive astrocytes show increased expression of active and inactive precursor forms of matrix metalloproteinase 2 (MMP-2), an enzyme that is able to degrade the extracellular matrix, directly enabling tumor invasion (bottom)." (PMID 39066464, 2025). "MMP‐2, secreted by activated fibroblasts, activates MMP‐14 at tumor cell filopodia, degrading the basement membrane and promoting cell extravasation." (PMID 40437741, 2025). "For example, DHA’s ability to reverse EMT markers (e.g., upregulation of E-Cadherin and downregulation of N-Cadherin, MMP-2, and MMP-9) suggests its potential to prevent tumor spread, a major challenge in NSCLC treatment." (PMID 40697663, 2025). "MMP2 and MMP9 produced by tumor cells are controlled by adipocyte-derived leptin and IL6 by activating FAK- and SRC-dependent pathways." (PMID 40841364, 2025). "To further explore the differences in metastasis and invasion among the three models, we examined the expression levels of MMP2 and MMP9, molecules involved in tumor metastasis." (PMID 41308696, 2025).
tumor (continued). "IL-6 also promoted angiogenesis, tumor invasion, and metastasis through the regulation of hypoxia-inducible factor 1α (HIF-1α), matrix metalloproteinases (MMP2, MMP7, MMP9), and vascular endothelial growth factor (VEGF)." (PMID 40160826, 2025). "The resulting peptide clamp is linked to the antibody via a protease-cleavable sequence sensitive to matrix metalloproteinases (MMPs), particularly MMP-2 and MMP-9, which are frequently overexpressed in the tumor microenvironment." (PMID 41246356, 2025). "These compounds have been reported to downregulate the activity and/or expression of MMP-2 and MMP-9, thus potentially suppressing tumor progression." (PMID 40563423, 2025). "Cardamonin reduced pro-tumor activity of TAMs, decreased M2 markers (CD163, CD206), and suppressed IL-6, VEGFα, MMP2, MMP9 secretion." (PMID 40330466, 2025). "The overproduction of MMP2/9 in cancer leads to the degradation of ECM, allowing tumor cells to invade other tissues and spread through metastasis and cell death, proliferation, and angiogenesis." (PMID 40035822, 2025). "DS@MA-LS showed extensive presence in the bloodstream, selectively aggregated in the tumor area, and cleaved the PEG cover by MMP2-mediated cutting." (PMID 40837737, 2025). "Based on the high expression of MMP‐2 in tumor ECM, the MMP‐2‐sensitive nanoparticles designed by researchers can achieve specific drug release at the lesion site." (PMID 40686923, 2025). "QRHXF also decreased MMP2 and MMP9 protein expression levels, mitigating ECM degradation in NSCLC and suppressing tumor migration and invasion." (PMID 40670983, 2025). "Although numerous in vitro studies have demonstrated the inhibitory effects of wine-derived compounds on MMP-2 and MMP-9 expression in tumor cells, translating these findings into in vivo contexts remains challenging." (PMID 40563423, 2025). "Significantly, Western blot tests demonstrated decreased levels of MMP2 and MMP9, pivotal elements in the spread of cancer, as they aid in breaking down the extracellular matrix and facilitating tumor metastasis." (PMID 38415456, 2025). "Overproduction of MMP2 or MMP9 leads to the breakdown of critical ECM and BM components, allowing tumor cells to escape and spread further." (PMID 40735254, 2025). "Fucoidan, for example, has been reported to downregulate MMP-2 and MMP-9, enzymes critical for extracellular matrix degradation and tumor invasion." (PMID 41311846, 2025). "In turn, mTOR activation has been shown to upregulate MMP-2 and MMP-9—downstream effectors that degrade the ECM and facilitate tumour cell invasion." (PMID 40860666, 2025). "Specifically, L1low cells upregulate matrix metalloproteinases MMP2 and MMP10, enzymes that degrade ECM components to facilitate tumor dissemination." (PMID 40770187, 2025). "We also demonstrated that these cellular features are, at least in part, due to the presence of tumor-supportive molecules such as TNF-α, Tenascin-C, MMP-2, and SDF-1α in the CM secretome of ASCs and OC cells." (PMID 40072102, 2025). "Highly expressed MMP2 and MMP9 can widely degrade various proteins on tumor cell membranes and have become important targets in the field of cancer treatment." (PMID 40563539, 2025). "Abnormal expression of metalloproteinases is regulated by HIF-1α, which induces the expression of MMP2, MMP9, ADAM10, etc., in tumor cells, hydrolyzing MICA and MICB on the surface of tumor cells and mediating immune escape." (PMID 40563539, 2025). "The SAM and SH3 domain-containing 1 (SASH1) overexpression significantly inhibited cell invasion and proliferation by downregulation of MMP-2 and MMP-9, suggesting its tumor-suppresive role via the FAK-related axis." (PMID 41148856, 2025). "MMP-2 and MMP-9, known to promote tumor invasion and metastasis by degrading the extracellular matrix and basement membrane, were significantly downregulated in APOC1-knockdown cells, as shown by Western blot analysis (P < 0.0001)." (PMID 39873475, 2025).
tumor (continued). "Macrophages usually exhibit M2-type features secreting IL-10, transforming growth factor β (TGF-β), and matrix metalloproteinase 2 (MMP-2) in HCC, which have immunosuppressive and tumor-promoting effects." (PMID 40180937, 2025). "Matrix metalloproteinases (MMPs), particularly MMP-2 and MMP-9, are crucial enzymes that degrade the ECM, significantly contributing to the remodeling of the extracellular environment and promoting tumor progression." (PMID 40670983, 2025). "In addition, whether other metalloproteinases are also regulated by HIF-1α to mediate the immune escape of tumor cells from the killing by NK cells, and whether common metalloproteinases (MMP2, MMP9, and ADAM10) are also regulated by factors parallel to HIF-1α, still require further research." (PMID 40563539, 2025). "One of the key players in this process is the matrix metalloproteinase (MMP) family, particularly MMP-2, which plays a vital role in extracellular matrix (ECM) degradation, facilitating tumor cell invasion and metastasis." (PMID 41155277, 2025). "The mechanism of metastasis in various tumors, including HNSCC, is induced by the cooperation of extracellular HSP90 with MMP-2 and MMP-9, which disrupts the extracellular matrix and leads to the dissemination of tumor cells and formation of metastasis." (PMID 41369386, 2025). "In this specific tumor subset MMP9, together with MMP2 and ZEB1, were more related to the metastatic subtype of this tissue." (PMID 40332096, 2025). "Ellagic acid downregulates vascular endothelial growth factor (VEGF) and matrix metalloproteinases (MMP-2, MMP-9), thereby impairing tumor vascularization and metastatic potential." (PMID 41226270, 2025). "These nanovesicles were constructed from lipid-based liposomes and functionalized with a matrix metalloproteinase-2 (MMP-2)-sensitive peptide, internalizing RGD (iRGD), and PPa, facilitating deep tumor penetration and precise drug release." (PMID 41345744, 2025). "After being activated by the tumour cell-produced factor EMMPRIN, pro-MMP-2, secreted by fibroblasts, is thought to interact with the membrane metalloproteasemases (MT-MMPs) of neoplastic cells." (PMID 40724562, 2025). "Prior research has shown that MMP2, MMP3, and MMP9 can modulate the breakdown of nearly all extracellular matrix constituents, hence enhancing tumour motility, invasion, and metastasis." (PMID 39858466, 2025). "Clone formation and cytotoxicity assays further substantiated MMP-2-triggered cleavage of the GPLGVRG peptide, leading to PEG5K shedding and enhanced cellular internalization, which collectively inhibited tumor cell proliferation and viability." (PMID 40732329, 2025). "While direct physical interactions between tumour cells and CAFs in a matrigel 3D environment released soluble accelerating factors including matrix metalloproteinases (MMP) and MMP-2." (PMID 41373503, 2025). "Upon tumor-specific MMP2/MMP9-mediated digestion, loaded Pep-4 neo-peptide was released, and competitively bound to HLA molecule on tumor cells." (PMID 39748060, 2025). "BDKRB2 can promote angiogenesis by increasing vascular permeability and upregulating vascular endothelial growth factor (VEGF) and can also promote tumor cell migration and invasion through TRPM7, MMP2, endothelin-1, and ERK signaling pathways." (PMID 40224547, 2025). "Studies have shown that high levels of MMP-2 and MMP-9 correlate with poor patient prognoses, greater tumor invasiveness, and shorter survival times." (PMID 40265458, 2025). "ZKSCAN3 plays an important role in tumor progression by regulating key molecules such as VEGF, ITGβ4, MMP2, MMP9, CCND1, and CCND2." (PMID 40723888, 2025). "Among MMPs, the overexpression of MMP-2 and MMP-9 and their increased activities are closely related to BM and ECM decomposition, which increased tumor cell invasion and migration ability." (PMID 40149594, 2025).
tumor (continued). "Matrix metalloproteinases (MMPs), particularly MMP-2 and MMP-9, are crucial enzymes that mediate ECM degradation and promote tumor invasion and metastasis." (PMID 40869090, 2025). "Matrix metalloproteinase 2 (MMP2) plays an important role in the migration and invasion of malignant tumor cells." (PMID 40520987, 2025). "A crucial mechanism by which EGFRvIII enhances OSCC invasion is through upregulation of matrix metalloproteinases (MMPs), particularly MMP2 and MMP9, which degrade ECM components to facilitate tumor dissemination." (PMID 40472740, 2025). "Galectin-1 is involved in tumor invasion, metastasis, and EMT as it controls the expression of MMP-2, MMP-9, and TIMP." (PMID 39996781, 2025). "Anti-metastatic effects emerge through MMP2 and MMP9 downregulation coupled with EMT reversal, as validated by immunohistochemical analyses in xenograft tumor tissues." (PMID 41511301, 2025). "Conversely, certain factors were downregulated in tumour cells, with END-1, MMP-2, and GPNMB showing a statistically significant reduction." (PMID 40869222, 2025). "CXCL8 and CXCL10 promote ECM degradation by inducing overexpression of MMP-2 and MMP-9, thereby creating a gateway for tumor cell invasion." (PMID 41445742, 2025). "This pathway enhances tumor invasiveness by facilitating epithelial–mesenchymal transition (EMT) and upregulating MMPs such as MMP-2 and MMP-9." (PMID 41153831, 2025). "This inhibition decreases the expression of key tumor-promoting factors like IL-6, VEGFα, MMP2, and MMP9, limiting the tumor-promoting environment created by TAMs." (PMID 40330466, 2025). "Western blot results subsequently displayed that HIPK4 knockdown significantly reduced HIPK4, TAp63-pS395, Ki67, MMP2, and MMP9 levels, but elevated EFEMP1 levels in tumor tissues." (PMID 40316017, 2025). "A study explored the role of MMP-2 in GBM, focusing on its effects on tumor progression, angiogenesis, and invasion, using a genetically engineered mouse model." (PMID 40265458, 2025). "For instance, the upregulation of miR-378 has been shown to promote brain metastasis via MMP-2, MMP-9, and VEGF regulation, which complements our observation of elevated pS6 and suggests a pro-metastatic tumor microenvironment." (PMID 40805225, 2025). "The MMP2‐sensitive segment enables selective activation within the TME, while pHLIP facilitates the anchoring of preS1 epitopes onto tumor cell membranes under acidic conditions typical of the TME." (PMID 40091501, 2025). "These polyphenols (e.g., caffeoylquinic acids) can also downregulate MMP-2 and MMP-9, limiting tumor cell proliferation and invasion." (PMID 41517157, 2025). "Its activation suppresses MMP2 and MMP9, which are involved in ECM degradation and tumor cell invasion." (PMID 40564023, 2025). "After FOXCUT and FOXC1 (an EMT-related gene) silencing, the expression levels of MMP2, MMP7, MMP9, and VEGF-A were downregulated, suggesting a possible role for the FOXC1/FOXCUT gene pair in tumor angiogenesis in OSCC." (PMID 41020820, 2025). "MMP2 and MMP9 are members of the MMP family and play a significant role in ECM degradation, thus promoting the migration of tumor cells and their ability to metastasize." (PMID 40566630, 2025). "The downregulation of TIMP-3 by miR-101 has been reported to increase the activity of MMPs, specifically MMP-2 and MMP-9, which in turn facilitate tumor cell invasion and migration." (PMID 40429954, 2025). "Faberidilactone A effectively suppressed HepG2 cell migration in vitro and downregulated phosphorylated FAK and MMP-2 expression, indicating its role in inhibiting the FAK pathway and, consequently, tumor metastasis." (PMID 40076318, 2025). "The system used an MMP-2-cleavable GPLGVRG segment, allowing the tumor-specific disassembly of micelleplex and exposure of the R9 peptide to enhance cellular uptake." (PMID 40756358, 2025).